OTUD5 (OTU deubiquitinase 5)
Diseases named in the same sentence as OTUD5 in open-access papers (continued):
Sharing a sentence is not in itself a finding about the gene and the disease.
tumor (continued). "Consistently, OTUD5 immunostaining was observed in normal lung and tumor cells, with higher staining in the control cells than in the cancer cells (left)." (PMID 32826889, 2020). "OTUD5 staining was observed to be distributed in both the nucleus and cytoplasm of the hepatocytes and tumor cells." (PMID 32826889, 2020). "OTUD5 expression was significantly correlated with tumor size, lymph node invasion and TNM stage in the NSCLC patients." (PMID 32826889, 2020). "For the first time, it was also suggested in this study that OTUD5 acted as a tumor suppressor in NSCLC." (PMID 32248621, 2020). "Results showed that OTUD5‐KO significantly suppressed tumour growth in vivo." (PMID 40070026, 2025). "Our data demonstrated that OTUD5 knockout significantly reduced tumour progression." (PMID 40070026, 2025). "Notably, the inhibitory effect of OTUD5‐KO on tumour growth was found to be comparable to that of nutlin‐3a treatment, with the combination of both treatments yielding the most pronounced inhibitory effect." (PMID 40070026, 2025). "In addition, analysis of Ki67 staining of tumour tissues revealed that OTUD5‐KO and nutlin‐3a treatment had similar inhibitory impacts on tumour proliferation, with the combined treatment exhibiting the most significant efficacy." (PMID 40070026, 2025). "In tumor cells, OTUD5 promotes tumor progression by deubiquitinating TRIM25." (PMID 38880876, 2024). "The expression and function of OTUD5 in these two tumor types are currently unknown and need to be further investigated." (PMID 37190070, 2023). "Based on our findings and others’, we speculate that the activation of OTUD5-mediated DBC1 deubiquitination may suppress tumor growth, which may provide a novel target for clinical tumor therapy." (PMID 35913115, 2022). "Above all, our findings demonstrated that miR-652-3p may abolish the tumor-suppressing role of OTUD5/PTEN, thereby facilitating NSCLC cell proliferation, invasion, and migration." (PMID 35765958, 2022). "In order to explore how OTUD5 affects tumor progression, we used mass spectrometry to detect the proteins that OTUD5 may bind." (PMID 36085200, 2022). "Two different tumor cell lines, Huh7 and Hep3B, were then used to investigate whether the siRNA-mediated depletion of OTUD5 promoted cell proliferation." (PMID 32826889, 2020). "Importantly, OTUD5 expression was significantly correlated with tumor grade, tumor size and TNM stage, suggesting that lower OTUD5 expression correlates with more aggressive disease in HCC patients." (PMID 32826889, 2020). "In vitro experiments validated the tumor‐suppressive function of OTUD5 in NSCLC." (PMID 32248621, 2020). "In summary, our results establish OTUD5 as a pivotal regulator of tumor progression." (PMID 32826889, 2020). "OTUD5 expression is markedly downregulated in tumor tissues." (PMID 32826889, 2020). "Notably, the expression pattern of OTUD5 in tumours clearly depends on the tissue type." (PMID 38658981, 2024). "However, another group reported a tumour-suppressive role of OTUD5 in HCC." (PMID 38658981, 2024). "Therefore, the interaction of OTUD5 in tumor and immunity deserves further investigation." (PMID 37190070, 2023). "Thus, OTUD5 knockdown was able to accelerate tumor growth in a nude mouse model." (PMID 37190070, 2023). "Importantly, OTUD5 knockdown accelerates tumor growth in a nude mouse model." (PMID 32826889, 2020). "Moreover, we demonstrate that OTUD5 plays a previously unknown role in transcriptional regulation and tumor suppression by deubiquitinating TRIM25, leading to the downregulation of PML and fewer PML-NBs." (PMID 32826889, 2020).
tumor (continued). "In this study, we discovered OTUD5 function in regulating cell proliferation and suppressing tumor, as demonstrated by the increased cell proliferation after RNAi-mediated OTUD5 knockdown and by the increased tumor growth after OTUD5 knockdown in a xenograft mouse model." (PMID 32826889, 2020). "OTUD5 knockdown significantly inhibited the growth of HCCLM3 cells in nude mice, as determined by the significant reductions in tumour volume and weight (P < 0.05)." (PMID 38658981, 2024). "Mechanistically, hypoxic stress promoted the interaction between DBC1 and SIAH2 and enhanced the disassociation of DBC1 from OTUD5, resulting in an increase in DBC1 ubiquitination and degradation, contributing to tumor cell proliferation and migration." (PMID 35913115, 2022). "Among the upregulated genes, MBNL2, SEPT4, REPS2, OTUD5, and TXNIP were shown to play a tumor-suppressive role in many tumors." (PMID 36428626, 2022). "Our study indicates that OTUD5, a member of the ovarian tumor protease (OTU) subfamily of DUBs, cooperates with TRIM25 in tumor suppression via deubiquitination activity." (PMID 34102455, 2021). "To assess the OTUD5-mediated PML regulation in tumor development under more physio pathologically relevant conditions, we also investigated PML expression and its correlation with OTUD5 levels in NSCLC." (PMID 32826889, 2020). "In the present study, bioinformatic analysis via high throughput RNA-sequencing data from TCGA indicated that low OTUD5 expression in CESC and was correlated with leading clinical features (tumor stage, nodal metastasis status) and overall survival." (PMID 32655987, 2020). "The tumor spheres derived from the OTUD5-depleted cells and PML-depleted cells grew faster and had greater weight than those excised from the control cells, while TRIM25 knockdown inhibited tumor sphere formation." (PMID 32826889, 2020). "Therefore, modulating OTUD5 phosphorylation may be a promising strategy for tumor treatment." (PMID 32826889, 2020). "The catalytic activity of OTUD5 is necessary for OTUD5 function, which is consistent with our findings that OTUD5 interacts with and deubiquitinates TRIM25 to inhibit tumor growth." (PMID 32826889, 2020). "The knockdown efficiency of OTUD5 and the levels of TRIM25 and PML in the tumor tissues formed by the OTUD5-depleted cells were determined by RT-PCR." (PMID 32826889, 2020). "Moreover, we examined OTUD5 and GPX4 protein levels in different groups of MFC tumour tissues collected." (PMID 40070026, 2025). "OTUD5, a member of the OTU family, has been shown to contribute to tumor progression." (PMID 38880876, 2024). "Our studies reveal a critical role of OTUD5 in tumorigenesis, as indicated through its interaction with TRIM25, suggesting that the OTUD5-TRIM25 axis acts as an important transcriptional regulator in tumor progression." (PMID 32826889, 2020). "Interestingly, we further confirmed that SIAH2 and OTUD5 competitively bind to DBC1 at the same N-terminal region, and hypoxia promotes the interaction of DBC1 with SIAH2 rather than OTUD5, resulting in ubiquitination and degradation of DBC1 to promote tumor progression." (PMID 35913115, 2022). "Importantly, OTUD5 expression was significantly and positively correlated with PML levels in both tumor and nontumor tissues, supporting the supposition that OTUD5 may regulate PML in NSCLC patients." (PMID 32826889, 2020).
cancer (12 papers, 2020 to 2025). A tumor composed of atypical neoplastic, often pleomorphic cells that invade other tissues. "The reduced OTUD5 level is associated with an aggressive phenotype and a poor clinical outcome for cancers patients." (PMID 32826889, 2020). "OTUD5 is a deubiquitinase associated with cancer development and innate immunity response." (PMID 37897511, 2023). "This diversity is attributed to the distinct target proteins of OTUD5 within various cancer types, leading to divergent impacts on tumourigenesis." (PMID 40070026, 2025). "Our results suggest that OTUD5 is an oncogene in HCC that controls the growth of cancer cells by deubiquitinating and stabilizing SLC38A1." (PMID 38658981, 2024). "OTUD5 is involved in the tumorigenesis and progression of several common cancers through the deubiquitination and stabilization of some key proteins or enzymes." (PMID 37190070, 2023). "The results suggested that, in these three cancers, the patients with low OTUD5 expression had a shorter survival (p < .05, log‐rank test)." (PMID 32248621, 2020). "Here, the authors perform an RNAi screen and identify that the deubiquitinase OTUD5 suppresses cancer growth in a TRIM25 dependent manner, which in turn controls the expression of tumour suppressor protein, PML." (PMID 32826889, 2020). "Recently, studies have shown that OTUD5 plays an indispensable role in cancer." (PMID 38658981, 2024). "In addition, the function of OTUD5 in a variety of cancers is beginning to be understood, with its different levels of expression and different functions in different tumors." (PMID 37190070, 2023). "The specific function of OTUD5 in different cancers needs to be analyzed on a case-to-case basis." (PMID 37190070, 2023). "OTUD5 not only promotes cancer development, but also inhibits the development of several cancers." (PMID 37190070, 2023). "Expression and clinical significance of OTUD5 in various cancers." (PMID 37190070, 2023). "Finally, we assessed the OTUD5 expression and its possible clinical significance in human cancers." (PMID 32826889, 2020). "Finally, we assess OTUD5 roles in a mouse xenograft model and human cancers." (PMID 32826889, 2020). "Ovarian tumour domain‐containing 5 (OTUD5), recognised as a DUB, plays different roles in different types of cancer." (PMID 40070026, 2025). "In this review, we comprehensively summarize the roles of seven DUBs with OTU structural domains in cancer progression and antiviral immune responses, including OTUD1, OTUD2, OTUD3, OTUD4, OTUD5, OTUD6A, and OTUD6B." (PMID 41050073, 2025). "A recent study reported that OTUD5 expression is strongly downregulated in HCC and that its knockdown accelerates cancer cell growth both in vitro and in vivo." (PMID 38658981, 2024). "OTUD5, a phosphorylation-activation-dependent DUB, is involved in various processes, such as DNA damage repair, inflammatory response, and innate immune response, and it has also been achieved in cancer research." (PMID 41050073, 2025). "Moreover, quite a few OTUs such as DUBA, OTUB1, OTUD1, and OTUD5 are involved in the regulation of the TIME and cancer immunotherapy." (PMID 36052059, 2022). "We treated control and OTUD5‐KO cells with nutlin‐3a and observed that knockout of OTUD5, in combination with nutlin‐3a treatment, led to a reduction in protein levels of OTUD5 and GPX4, thereby triggering ferroptosis in cancer cells and consequently inhibiting cell proliferation." (PMID 40070026, 2025).
heart disease (1 paper, 2023). "Taken together, we conclude that OTUD5 overexpression offers a safer and more effective treatment for I/R‐induced heart disease." (PMID 37552043, 2023).
immune disorders (1 paper, 2025). "Elucidation of molecular mechanisms underlying such opposing effects on type I IFN responses by OTUD3 and OTUD5 and the identification of key molecules linked to both OTUDs may open up a new avenue for the development of novel treatments in patients with immune disorders including IBD." (PMID 41155222, 2025).
infection (1 paper, 2023). The state of being infected such as from the introduction of a foreign agent such as serum, vaccine, antigenic substance or organism. "Among these, one group containing OTUB1, OTUB2, OTUD4, OTUD5, OTUD6B, and OTUD7B showed obvious upregulation 6 h post-infection, followed by downregulation 12 h post-infection." (PMID 37650650, 2023).
kidney diseases (1 paper, 2023). "Overall, this study highlights a new autophagy-dependent ferroptosis module: hypoxia/ischemia-induced OTUD5 autophagy triggers GPX4 degradation, offering a potential therapeutic avenue for I/R-related kidney diseases." (PMID 38110369, 2023).
OTUD5 also shares sentences with these, for which no sentence is quoted: primary biliary cholangitis (3 papers); viral infection (3); colon cancer (2); neurodevelopmental disorder (2); Alzheimer disease (1); Autoimmunity (1); cardiovascular disease (1); Congenital Malformation (1); ischemic stroke (1); lung squamous cell carcinoma (1); myocardial ischemia (1); ovarian carcinoma (1); pancreatic cancer (1); Parkinson disease (1); small cell lung carcinoma (1); X-linked mental retardation 3 (1).